C15orf40 (chromosome 15 open reading frame 40)
Synonyms: MGC29937
Tractability: PROTAC: ubiquitination databases record sites on it; its protein half-life has been measured.
Gene: Protein-coding gene on chromosome 15 (82,988,441 to 83,011,641, reverse strand). Ensembl gene ENSG00000169609.
Subcellular location (Human Protein Atlas): Golgi apparatus; Nucleoplasm
Gene Ontology:
Cellular component: mitochondrion; cytoplasm
Genetic constraint (gnomAD): Loss-of-function variants: 7 observed, 12.29 expected, observed/expected ratio (o/e) 0.57, 90% interval 0.32 to 1.07. The synonymous counts are far from expectation, so gnomAD's model fits this gene poorly and the ratio says little. Missense variants: 201 observed, 175.19 expected, observed/expected ratio (o/e) 1.15, 90% interval 1.02 to 1.29. Synonymous variants: 86 observed, 64.75 expected, observed/expected ratio (o/e) 1.33, 90% interval 1.12 to 1.59.
Homologues: Orthologues: pig C15orf40 (86% identical), rabbit C15orf40 (82% identical), chimpanzee C15H15orf40 (80% identical), guinea pig C15orf40 (73% identical), mouse 3110040N11Rik (70% identical).